DYRK1A (dual specificity tyrosine phosphorylation regulated kinase 1A)
Description:
Dual-specificity kinase which possesses both serine/threonine and tyrosine kinase activities. Exhibits a substrate preference for proline at position P+1 and arginine at position P-3. Plays an important role in double-strand breaks (DSBs) repair following DNA damage. Mechanistically, phosphorylates RNF169 and increases its ability to block accumulation of TP53BP1 at the DSB sites thereby promoting homologous recombination repair (HRR). Also acts as a positive regulator of transcription by acting as a CTD kinase that mediates phosphorylation of the CTD (C-terminal domain) of the large subunit of RNA polymerase II (RNAP II) POLR2A. May play a role in a signaling pathway regulating nuclear functions of cell proliferation. Modulates alternative splicing by phosphorylating the splice factor SRSF6 (By similarity). Has pro-survival function and negatively regulates the apoptotic process (By similarity). Promotes cell survival upon genotoxic stress through phosphorylation of SIRT1 (By similarity). Phosphorylates SEPTIN4, SEPTIN5 and SF3B1 at 'Thr-434' (By similarity).
Synonyms: MNBH; DYRK; MNB; DYRK1; HP86; MRD7
Tractability: Small molecule: a structure with a bound ligand is known; a high-quality ligand is known; it has a high-quality binding pocket; it belongs to a druggable protein family. PROTAC: ubiquitination databases record sites on it; its protein half-life has been measured; a small molecule that binds it is known.
Target class: Kinase; CMGC protein kinase Dyrk1 subfamily; Enzyme; CMGC protein kinase group; CMGC protein kinase DYRK family; Protein Kinase
Chemical probes: KH-CB19 (high quality), KuFal194, MU1210 (high quality), PD083310
Gene: Protein-coding gene on chromosome 21 (37,365,573 to 37,526,358, forward strand). Ensembl gene ENSG00000157540.
Subcellular location: Nucleus; Nucleus speckle
Subcellular location (Human Protein Atlas): Nuclear speckles; Centrosome; Cytosol; Nucleoplasm
Pathways (Reactome):
Cell Cycle: G0 and Early G1
Gene Ontology:
Molecular function: histone H3T45 kinase activity; non-membrane spanning protein tyrosine kinase activity; protein binding; protein serine kinase activity; protein serine/threonine kinase activity; protein tyrosine kinase activity; RNA polymerase II CTD heptapeptide repeat kinase activity; tau protein binding; protein kinase activity; splicing factor binding; tau-protein kinase activity; transcription coactivator activity; ATP binding; protein serine/threonine/tyrosine kinase activity
Biological process: negative regulation of heterochromatin formation; peptidyl-tyrosine phosphorylation; positive regulation of double-strand break repair; positive regulation of RNA splicing; regulation of amyloid-beta formation; regulation of neurofibrillary tangle assembly; circadian rhythm; negative regulation of microtubule polymerization; nervous system development; positive regulation of DNA-templated transcription; protein autophosphorylation; protein phosphorylation; regulation of alternative mRNA splicing, via spliceosome; chromatin remodeling; regulation of transcription by RNA polymerase II
Cellular component: cytoplasm; cytoskeleton; nuclear speck; nucleoplasm; nucleus; axon; dendrite
Genetic constraint (gnomAD): Loss-of-function variants: 7 observed, 76.47 expected, observed/expected ratio (o/e) 0.0915, 90% interval 0.051 to 0.17. The upper end of that interval is the gene's LOEUF score, 0.17, which puts it in group 1 of 6, group 1 being the genes least tolerant of losing a copy. Missense variants: 611 observed, 960.72 expected, observed/expected ratio (o/e) 0.64, 90% interval 0.59 to 0.68. Synonymous variants: 345 observed, 337.72 expected, observed/expected ratio (o/e) 1.02, 90% interval 0.94 to 1.12.
Gene-disease validity (ClinGen):
ClinGen rates the evidence that DYRK1A causes each of these diseases.
complex neurodevelopmental disorder (autosomal dominant): Definitive. A disorder that involves more than one phenotype associated with the central nervous system, including but not limited to intellectual disability, autism, and seizures (epilepsy).
Homologues: Orthologues: chimpanzee DYRK1A (100% identical), dog DYRK1A (99% identical), macaque DYRK1A (99% identical), pig DYRK1A (99% identical), rabbit DYRK1A (99% identical), rat Dyrk1a (99% identical), guinea pig DYRK1A (99% identical), mouse Dyrk1a (99% identical), tropical clawed frog dyrk1a (94% identical), zebrafish dyrk1ab (80% identical), zebrafish dyrk1aa (79% identical), Drosophila melanogaster mnb (57% identical), and 3 more. Paralogues in human: DYRK1B (54% identical), HIPK2 (24% identical), HIPK3 (24% identical), HIPK1 (23% identical), DYRK2 (22% identical), DYRK4 (21% identical), DYRK3 (20% identical), CLK2 (18% identical), CLK3 (18% identical), CLK4 (17% identical), CLK1 (17% identical), HIPK4 (17% identical).
Diseases named in the same sentence as DYRK1A in open-access papers:
DYRK1A is named in the same sentence as 193 diseases in open-access papers, as found by Europe PMC text mining. Sharing a sentence is not in itself a finding about the gene and the disease. The quoted sentences say what the papers report.
Down syndrome (207 papers, 2006 to 2026). "Significant research has characterized the role of DYRK1A in neuronal development, and a smaller body of work has also implicated its role in normal B cell differentiation and in Down syndrome (DS)-associated ALL and CRLF2-R Ph-like ALL." (PMID 40148558, 2025). "Recent studies have implicated DYRK1A is closely associated with pathoprogression of neurocognitive disorders, including AD and Down syndrome." (PMID 41306975, 2025). "Increased DYRK1A activity is linked to several neurodevelopmental disorders including Down syndrome but has only recently been proposed as a Rab-phosphorylating kinase." (PMID 40905990, 2025). "Chromosome 21 DYRK1A kinase is associated with a variety of neuronal diseases including Down syndrome." (PMID 40003558, 2025). "DYRK1A (dual-specificity tyrosine-phosphorylation-regulated kinase 1 A) is a serine/threonine kinase that has been implicated in Down syndrome, a human condition caused by trisomy of chromosome 21." (PMID 39633007, 2025). "Given that DYRK1A is important for Down Syndrome-associated ALL and the closely related CRLF2-R ALL, we therefore excluded these ALL types from our analysis." (PMID 40148558, 2025). "Previous studies have suggested the involvement of DYRK1A in Down syndrome-associated megakaryoblastic leukemia and normal hematopoiesis." (PMID 40148558, 2025). "DYRK1A gene dosage imbalance has been associated with multiple disorders affecting both cognitive ability and skeletal health, including Down syndrome (DS), Alzheimer’s disease (AD), Parkinson’s disease (PD), and Huntington disease (HD)." (PMID 39308945, 2024). "DYRK1A is considered a significant gene in the Down syndrome phenotype and has been implicated in other neurological malformations, some of which are seen in congenital CMV infection." (PMID 38932210, 2024). "Skeletal phenotypes associated with haploinsufficiency (1 copy – DYRK1A syndrome) or trisomy (3 copies – Down syndrome) of DYRK1A." (PMID 39308945, 2024). "DYRK1A, a ubiquitously expressed kinase, is linked to the dominant intellectual developmental disorder, microcephaly, and Down syndrome in humans." (PMID 39436397, 2024). "DYRK1A has been implicated in the development of cognitive phenotypes associated with many genetic disorders, including Down syndrome (DS) and Alzheimer’s disease (AD)." (PMID 39308945, 2024). "Overexpression of DYRK1A is strongly associated with Down syndrome, whereas haploinsufficiency is associated with MRD7." (PMID 39109359, 2024). "Conversely, overexpression of DYRK1A also confers neurodevelopmental risk, as it is believed to contribute to neurocognitive deficits associated with Down syndrome." (PMID 39840013, 2024). "In humans, the DYRK1A gene is located on chromosome 21, and through studies in mouse models, DYRK1A copy number has been shown to play a causative role in Down syndrome neurodevelopmental defects." (PMID 39271109, 2024). "DYRK1A is an essential gene in mammals, whose alterations in expression have been associated with different human diseases including Down syndrome when present in trisomy or a neurodevelopmental syndrome when in haploinsufficiency." (PMID 39405283, 2024). "The identification of FAM53C as a suppressive binding partner for DYRK1A sheds new light on the molecular mechanism of Down syndrome caused by triplication of DYRK1A in human chromosome 21." (PMID 37802655, 2023). "In Down syndrome (also known as trisomy 21), there is an extra copy of DYRK1A, resulting in overexpression that is strongly associated with disease pathogenesis and neurological developmental delay." (PMID 37310920, 2023). "The effect can be achieved by carefully tailoring the selectivity of inhibitor toward a particular kinase, especially DYRK1A, previously associated with Down syndrome and Alzheimer's disease." (PMID 37872245, 2023). "The protein kinase DYRK1A encoded in human chromosome 21 is the major contributor to the multiple symptoms observed in Down syndrome patients." (PMID 37802655, 2023).
Down syndrome (continued). "Human Dual specificity tyrosine (Y)-Regulated Kinase 1A (DYRK1A) is encoded by a dosage-dependent gene located in the Down syndrome critical region of human chromosome 21." (PMID 37900285, 2023). "DYRK1A is an enzyme that has been implicated as an important drug target in various therapeutic areas, including neurological disorders (Down syndrome and Alzheimer’s disease), oncology, and type 2 diabetes (pancreatic β-cell expansion)." (PMID 36986543, 2023). "DYRK1A is a kinase implicated in various forms of cancer, neurodegenerative disease, and Down’s Syndrome." (PMID 35989379, 2022). "Bone abnormalities affect all individuals with Down syndrome (DS) and are linked to abnormal expression of DYRK1A, a gene found in three copies in people with DS and Ts65Dn DS model mice." (PMID 35196359, 2022). "In humans, the MBK-1 ortholog DYRK1A is associated with a variety of disorders, most prominently with neurological defects observed in Down syndrome." (PMID 34983389, 2022). "We also provide evidence of catechin effects on DYRK1A, a dosage-sensitive gene encoding a protein kinase involved in brain defects and metabolic disease associated with Down syndrome." (PMID 35631180, 2022). "Deregulated DYRK1A activity has been linked to Down syndrome (DS), Intellectual Developmental Disorder Autosomal Dominant 7 (MRD7), dementia, AD, Fronto-Temporal Degeneration (FTD), Huntington’s disease (HD) and Parkinson’s disease (PD)." (PMID 36012629, 2022). "Altered DYRK1A gene expression due to trisomy 21 (Down syndrome) has been linked to the pathogenesis of several conditions in Down syndrome including alterations in neuronal development, cognitive defects, heart defects, and hematological malignancies." (PMID 35596909, 2022). "Among them, the DYRK1A protein kinase is thought to be implicated in Alzheimer’s disease (AD) and Down syndrome, and as such, has emerged as an appealing therapeutic target." (PMID 36615235, 2022). "DYRK1A encodes a protein kinase involved in the neuropathology associated with Down syndrome that influences neurogenesis and the morphological differentiation of neurons." (PMID 36402907, 2022). "Human DYRK1A maps to chromosome 21q22.13 in the Down syndrome critical region, and its overexpression has been implicated in the neurological defects associated with this disorder." (PMID 34983389, 2022). "Multiple approaches indicated specific involvement of the DYRK1A isoform, which has been linked to Mk leukemogenesis in Down syndrome." (PMID 35925681, 2022). "Overexpression of DYRK1A, on the other hand, has been linked with learning and memory defects observed in people with Down syndrome (DS)." (PMID 34587162, 2021). "Overdosage of DYRK1A associated with the DSCR1 gene (resident of the “Down syndrome candidate region” and as a shock or stress gene) was reported to diminish NFATc activity in the immune response." (PMID 34445786, 2021). "The DYRK1A-TOM70 axis will enable insights into disease mechanisms caused by dysfunctional DYRK1A, including autism spectrum disorder, microcephaly and Down syndrome." (PMID 34257281, 2021). "DYRK1A is located on chromosome 21q22.13 within the critical region causing Down syndrome (also known as Trisomy 21)." (PMID 33562844, 2021). "Triallelic DYRK1A is implicated in the neuropathology of Down syndrome, whereas haploinsufficiency causes the rare DYRK1A-related intellectual disability syndrome (also known as mental retardation 7)." (PMID 33562844, 2021). "DYRK1A is located within the Down syndrome critical region on chromosome 21, and increased doses of DYRK1A have been implicated in Down syndrome pathobiology." (PMID 32467234, 2020). "This excess of DYRK1A has been implicated in several pathological traits of Down syndrome, including the increased risk of childhood leukaemia, skeletal abnormalities, intellectual disability, motor coordination and retinal defects." (PMID 30979931, 2019).
Down syndrome (continued). "Mutations in DYRK1A underlie a spectrum of human developmental disorders, and increased dosage in trisomy 21 is implicated in Down syndrome related pathologies." (PMID 31024071, 2019). "DYRK1A is located in a Down syndrome critical region (DSCR) and is best known as a major causative gene that is implicated in brain function, neurological defects and neurofibrillary tangle formation in Down syndrome (DS)." (PMID 31043432, 2019). "Since hyperactivity of the protein kinase DYRK1A is linked to several neurodegenerative disorders, DYRK1A inhibitors have been suggested as potential therapeutics for Down syndrome and Alzheimer’s disease." (PMID 31766108, 2019). "The characteristic symptom of Down syndrome, intellectual disability, has been linked to this overexpression of DYRK1A." (PMID 31766108, 2019). "Further, DYRK1A is located on the Down’s Syndrome Critical Region of chromosome 21 and has been linked to the characteristic facial features associated with this disorder." (PMID 30390632, 2018). "Pharmacological inhibition of DYRK1A is currently under consideration for the treatment of conditions in which it is overexpressed (Down syndrome and Alzheimer disease) as well as Down syndrome-associated pediatric leukemia." (PMID 29942794, 2018). "Overexpression of DYRK1A is considered a major cause of the neurodevelopmental alterations that underlie altered brain function in Down syndrome (Tejedor and Hämmerle, 2011; Duchon and Herault, 2016)." (PMID 29700199, 2018). "None of the enriched sets of pathways and functions associated with SCN1A was associated with the Down syndrome genes (DYRK1A, PSMG1, RCAN1, DSCR3, DSCR4) or with TSC2." (PMID 29518120, 2018). "DYRK1A gene in human localizes to the Down syndrome critical region q22.2 of chromosome 21, and its overexpression is associated with abnormal phenotype of Down syndrome patients." (PMID 29127398, 2017). "As a candidate gene responsible for learning defects associated with Down syndrome and Alzheimer’s disease (AD), DYRK1A has been implied to play pivotal roles in cell proliferation and brain development." (PMID 28775333, 2017). "The gene encoding Dyrk1a is located on chromosome 21, within the Down syndrome (DS) critical region." (PMID 28779511, 2017). "DYRK1A is important in neuronal development and function, and its excessive activity is considered a significant pathogenic factor in Down syndrome and Alzheimer's disease." (PMID 27483355, 2016). "Enhanced activity and overexpression of DYRK1A have been linked to altered brain development and function in Down syndrome and neurodegenerative diseases such as Alzheimer’s disease." (PMID 26192590, 2015). "The transcription of miR-1246 is activated by these genes and miR-1246, in turn, downregulates DYRK1A, a Down syndrome-associated protein kinase, establishing a link between cancer and Down syndrome." (PMID 25880556, 2015). "The Down syndrome-associated DYRK1A kinase has been reported as a stimulator of the developmentally important Hedgehog (Hh) pathway, but cells from Down syndrome patients paradoxically display reduced Hh signalling activity." (PMID 26310823, 2015). "Owing to the localisation of the human DYRK1A gene on chromosome 21, the over-activity of DYRK1A that results from the increased dosage of the DYRK1A gene is thought to contribute to the neurological abnormalities associated with Down syndrome." (PMID 26192590, 2015). "DYRK1A is both overexpressed in AD brain material and duplicated in the critical region of chromosome 21 in Down's syndrome which is associated with early onset AD." (PMID 24429107, 2014).